CD55 (CD55 molecule (Cromer blood group))
Diseases named in the same sentence as CD55 in open-access papers (continued):
Sharing a sentence is not in itself a finding about the gene and the disease.
viral infection (10 papers, 2014 to 2025). "The regulation of inflammation by CD55 has been reported in viral infections and immune-mediated diseases." (PMID 38542433, 2024). "Notably, increased expression of complement regulatory proteins (e.g. CD35, CD55, CD46, and CD69) on neutrophils and monocytes has been associated with bacterial and viral infections." (PMID 40568581, 2025). "Since CD55 is a cell-surface-bound glycoprotein acting as a complement inhibitor, its overexpression is suggested to play a role in self-protection due to complement overactivation in case of viral infection and further prevention of host cell damage." (PMID 37795240, 2023). "Collectively, scRNA-seq data analysis of the three cell culture models showed expression of CDHR3, CD55 and ACE2 receptors in ciliated, secretory and basal cells, suggesting the possibility of modeling ssRNA virus infection, including SARS-CoV-2, in the airway epithelium in vitro." (PMID 37569398, 2023).
melanoma (9 papers, 2011 to 2025). A malignant, usually aggressive tumor composed of atypical, neoplastic melanocytes. "The T cell immunoreceptor with Ig and ITIM domains (TIGIT)/CD55 axis contributes to immune suppression by suppressing T cell recruitment and activation, thereby reducing the immune system’s ability to target melanoma cells effectively." (PMID 40872475, 2025). "Overexpression of intercellular adhesion molecule 1 (ICAM-1; also known as CD54) and decay acceleration factor (DAF; also known as CD55) in melanoma, multiple myeloma, and breast cancers allows entry of coxsackie viruses into tumor cells." (PMID 37040283, 2023). "5-azacytidine was shown to elevate the levels of CD55 and CD59 in Burkitt lymphoma cell lines but only of CD59 in melanoma cells." (PMID 31024572, 2019).
diabetes (8 papers, 2006 to 2025). "Increased glycosylation has been implicated in inactivation of complement regulators in diabetes, and patients with advanced diabetic retinopathy have a reduction in the complement regulators CD55 and CD59 and increased deposition of MAC in their ocular vasculature." (PMID 24167638, 2013). "It has been reported that increased plasma levels of APEX1, CD55, PSME2, and SERPINC1 are significantly associated with hypertension, and increased plasma levels of APEX1, CD55, GGCT, KRT17, PSME2, and SERPINC1 are associated with diabetes." (PMID 41156831, 2025). "Following adjustment for age, sex, BMI, alcohol consumption status, vascular/heart diseases, diabetes, medications for cholesterol, blood pressure, or diabetes, and exogenous hormone use, CD55, CFHR4, and CFHR5 were found to exhibit significant associations with AMD." (PMID 40735363, 2025). "Here we report that NICC from genetically modified (GM) pigs deleted for αGal and expressing the human complement regulators CD55 and CD59 can cure diabetes long-term in immunosuppressed baboons, with maximum graft survival exceeding 22 months." (PMID 35784286, 2022).
influenza (7 papers, 2015 to 2024). An acute viral infection of the respiratory tract, occurring in isolated cases, in epidemics, or in pandemics; it is caused by serologically different strains of viruses (influenzaviruses) designated A, B, and C, has a 3-day incubation period, and usually lasts for 3 to 10 days. "The association between IFITM3 rs12252, and CD55 rs2564978 SNPs and influenza H7N9/H1N1 pdm09 clinical outcomes was examined in Chinese population." (PMID 33766078, 2021). "Several polymorphisms which have been known for the susceptibility to influenza infection include CD55, C1QBP, FCGR2A, IFITM3, TNF, RPAIN, LTA and KIR." (PMID 33766078, 2021). "Studies have shown that the T/T genotype in the rs2564978 CD55 gene promoter is associated with severe influenza A (H1N1) pdm09." (PMID 33766078, 2021). "A 21-bp deletion in the promoter region of CD55 (rs150046210) is associated with a lower transcriptional activity and CD55 expression levels and with more severe influenza infections and allergic respiratory diseases." (PMID 29867953, 2018). "For CD55, within 100 Kb of the reported SNP, only two SNPs were available in our array, one of which, rs2564978, was significantly associated with influenza severity (p = 0.00638, OR = 7.11, 95% CI 1.4–36)." (PMID 26379185, 2015). "Interestingly, polymorphisms causing functional variation in CD55 have been implicated in severe influenza infection." (PMID 35250994, 2022). "Additional mutations associated with severe influenza have been described in the complement factor CD55/DAF, the pulmonary surfactant protein SFTPA2, the protease TMPRSS2, the endothelial transcriptional activator GATA2, interferon regulators IRF7 and IRF9, and the endosomal dsRNA receptor TLR3." (PMID 34524075, 2021). "A genome-wide association study (GWAS) indicated the complement regulatory protein CD55 as a possible candidate for severe A influenza; indeed, genotype rs2564978*T/T in CD55 showed an OR = 1.75 (P = 0.011) in 177 severe vs. 248 mild Chinese A(H1N1) cases." (PMID 26379185, 2015). "Previous study showed that two complement-related SNPs, rare TT genotype of CD55 and rare AA genotype of C1QBP, were associated with increased death risk of influenza, which indicated that mutations related to immunity may affect the prognosis." (PMID 39014398, 2024).
leukemia (7 papers, 2017 to 2026). A malignant (clonal) hematologic disorder, involving hematopoietic stem cells and characterized by the presence of primitive or atypical myeloid or lymphoid cells in the bone marrow and the blood. "The current study investigates the differential expression of membrane-bound complement regulatory proteins; CD46 and CD55 in leukemia." (PMID 41526546, 2026). "Flow cytometric analysis conducted for proteomic expression of CD46 and CD55 on cell surfaces of leukemia patients showed a reduction in expression by 1.2-fold and 2.8-fold in AML patients, respectively." (PMID 41526546, 2026). "mCRP, CD55 accelerates C3 convertase degradation and is overexpressed on the cell surface of several cancers such as leukemia." (PMID 39125875, 2024). "Furthermore, the level of CD46 and CD55 gene expression was compared in male and female leukemia patients to investigate if gender difference affects their gene expression." (PMID 41526546, 2026). "Downregulation of the expression of mCRPs CD46, CD55, and CD59 improved the efficacy of rituximab and the anti-CD20 mAb ofatumumab in lymphoma and leukemia cell lines and primary CLL samples." (PMID 28658265, 2017). "However, in leukemic mice they were abundant and predominantly FcγRII/III+CD55–, similar to NMPs, with a small FcγRII/III+CD55+ population observed selectively in KLG-E leukemias." (PMID 32330454, 2020).
lymphoma (7 papers, 2013 to 2023). A malignant (clonal) proliferation of B- lymphocytes or T- lymphocytes which involves the lymph nodes, bone marrow and/or extranodal sites. "However, the only association observed in this experiment was between the expression of CD55 versus CD59 in the lymphoma cells lines, perhaps reflecting their coordinated activity in complement inhibition (R2 = 0.94)." (PMID 23638367, 2013). "In various cancer cell lines, including rituximab-resistant lymphoma cells, the SBU-CD55 × CD20 antibody showed significantly higher CDC activity than either anti-CD20 IgG antibody alone or a combination of anti-CD20 IgG antibody and anti-CD55 IgG antibody." (PMID 37880350, 2023). "Bispecific antibodies targeting both CD20 and CD55 or CD20 and CD59 were also shown to potentiate the CDC of CD20-positive lymphoma cells in vitro and to prevent the growth of human lymphoma cells in SCID mice." (PMID 31024572, 2019). "Given the remarkable differences observed for the lymphoma cell lines, we subsequently assessed the functional consequences of distinct CD20, CD55 and CD59 expression for induction of complement-dependent cell lysis (CDC) induced by the different CD20-specific IgG." (PMID 33505398, 2020). "Previous studies suggested that the up-regulation of complement regulation proteins (CRPs) such as CD55 and CD59 on surface of lymphoma cells inhibits the activation of complement systems, which might be the main cause of resistant cells’ unresponsiveness to Rituximab mediated CDC in vitro." (PMID 26284588, 2015).
rheumatoid arthritis (7 papers, 2012 to 2024). A chronic, systemic autoimmune disorder characterized by inflammation in the synovial membranes and articular surfaces. "More recently, strong expression of CD55 on chondrocyte surfaces was demonstrated, and it was found that that CD55 is upregulated by stimulation with IL-1 in rheumatoid arthritis patients." (PMID 30473747, 2018). "KEGG pathway analysis of the upregulated proteins in ENTPD1+CD55+ cells indicated enrichment for proteins involved in rheumatoid arthritis (e.g., HLA-DRA, ICAM1) and ECM–receptor interaction (e.g., type I collagen, Laminin subunit alpha-5, integrin-subunit alpha-6)." (PMID 38612896, 2024). "sequenced 20387 single cells from synovial tissue of 5 patients with rheumatoid arthritis, and found three different subpopulations of RA synovial fibroblasts, which can be divided into two groups according to different surface markers, one is CD55+ synovial fibroblast, the other is CD90+ subset." (PMID 34349767, 2021). "CD55 was expressed at equal levels on FLS isolated from patients with rheumatoid arthritis (RA), osteoarthritis, psoriatic arthritis and spondyloarthritis." (PMID 22590509, 2012). "Regulation of complement inhibitors (CD55, CD35, CD59, and CD46) is important in autoantibody-mediated complement activation and is impaired in autoimmune diseases such as SLE, rheumatoid arthritis, and bullous pemphigoid." (PMID 30473747, 2018). "In our study, however, we recorded decreased CD55 expression after stimulating cultured HaCaT human keratinocytes with the cytokines TNF-α or IFN-γ, contrary to findings in other autoimmune diseases such as rheumatoid arthritis and SLE." (PMID 30473747, 2018).
systemic lupus erythematosus (7 papers, 2014 to 2023). An autoimmune multi-organ disease typically associated with vasculopathy and autoantibody production. "It has been reported that a decrease in the mean fluorescence intensity of CD55 was observed in T and B lymphocytes from systemic lupus erythematosus patients, implicating this marker as a possible player in lymphopenia." (PMID 35720411, 2022). "Among the surface molecules, the expression of CD55, CD86, CD93, and CCR6 were decreased in G-MDSCs from pristane-induce lupus mice, and INK128 could increase the expression of these genes." (PMID 34282122, 2021).
atherosclerosis (6 papers, 2012 to 2023). A disease characterized by the build-up of fatty material and calcium deposition in the arterial wall resulting in partial or complete occlusion of the arterial lumen. "CD55 deficiency has also been shown to protect apoE−/− micefrom atherosclerosis." (PMID 27551317, 2016). "CD55 is part of the complement system and has been suggested to play a role in the pathogenesis of atherosclerosis." (PMID 27551317, 2016). "Together, these data suggest that CD55 plays an essential role in downregulating generation of C3a and C5a and indicates a role for C3a and C5a in atherosclerosis and restenosis through interactions with their respective receptors." (PMID 24278688, 2012). "Thus, for example, lack of CD55 or CD59 in atherosclerosis-susceptible ApoE−/− mice, resulted in worse disease, while CD59 administration reduced the severity of experimental atherosclerosis by abrogating MAC formation." (PMID 31555668, 2019).
Burkitt lymphoma (6 papers, 2015 to 2022). A rare form of malignant mature B-cell non-Hodgkin lymphoma. "These Abs were able to recognize CD20 expressed on Burkitt's lymphoma cell lines and to neutralize membrane-bound CD55 and CD59 enhancing cell susceptibility to C-mediated lysis." (PMID 30319647, 2018). "We permanently transfected Daudi cells (PIG-Y-deficient human Burkitt's lymphoma cell line) with wild-type (WT) or p.Leu46Pro mutant vector constructs driven by the weak promoter followed by assessment of cell surface expression of CD55 and CD59 by FACS analysis." (PMID 26293662, 2015). "Neutralization of complement inhibitors as a concept to increase the efficacy of therapeutic antibodies was exploited by testing bi-specific antibodies targeting CD20 and CD55 either in vitro or in a murine xenograft model of Burkitt lymphoma." (PMID 35267578, 2022).
cervical carcinoma (6 papers, 2009 to 2025). A carcinoma arising from either the exocervical squamous epithelium or the endocervical glandular epithelium. "CRISPR/cas9-knockout of CD55 in cervical cancer C33A cells suppressed their proliferative and self-renewal capabilities, sensitized cells to radiation, and decreased tumorigenicity in vivo." (PMID 38612911, 2024). "Cervical carcinoma cells were rendered more susceptible to complement after treatment with blocking antibodies to CD59 and CD55, and lysis was increased further when cells were treated with both antibodies." (PMID 35227072, 2022). "Similarly in cervical cancer, CD55+ C33A cells display significant sphere-forming and migratory abilities, as well as enhanced tumorigenesis and radioresistance." (PMID 38612911, 2024). "Some research confirmed a novel affiliation between HPV-E6 oncoprotein expression and the increase in the CD55 and CD71 floor markers in most cervical cancer cells." (PMID 36479105, 2022). "The knockdown or knockout of CD55 and CD71 expression in HPV-E6-expressing cells should reverse the tumorigenic phenotypes of most cervical cancer cells." (PMID 36479105, 2022).
osteosarcoma (6 papers, 2005 to 2025). A usually aggressive malignant bone-forming mesenchymal neoplasm, predominantly affecting adolescents and young adults. "In vitro, endothelial cells, HeLa cells as well as osteosarcoma and colorectal cells release CD55 in a soluble form or deposit it into their extracellular matrix." (PMID 31024572, 2019). "105AD7 is a human monoclonal antibody that mimics the complement regulatory protein, CD55, overexpressed by many solid tumours including osteosarcoma." (PMID 15798769, 2005). "High levels of CD55 released from dying osteosarcoma tumours presented in the context of inflammation may overcome immune ignorance or tolerance associated with this self-antigen." (PMID 15798769, 2005). "Vaccination of colorectal and osteosarcoma patients with 105AD7 mAb in alum alone or with BCG in the first immunization, either failed to induce an anti-anti-idiotypic antibody response or induced a weak response against CD55, but it was able to activate both anti-Ab2 and anti-CD55 T cell responses." (PMID 23162790, 2012).
autoimmune hemolytic anemia (5 papers, 2011 to 2025). Autoimmune hemolytic anemia (AIHA) is an autoimmune disorder in which various types of auto-antibodies are directed against red blood cells causing their survival to be shortened and resulting in hemolytic anemia. "Deficient expression of CD55 and CD59 has recently been reported in patients with autoimmune hemolytic anemia, autoimmune thrombocytopenia, or SLE." (PMID 22081908, 2011). "However, decreased complement regulatory components on lymphocytes and erythrocytes, including CD55 and CD59, have been shown to be associated with lymphopenia and autoimmune hemolytic anemia (AHIA)." (PMID 24592327, 2014).
lymphopenia (5 papers, 2012 to 2022). Reduction in the number of lymphocytes. "Compared with healthy controls, we observed in SLE patients with lymphopenia and neutropenia decreased expression of CD55, CD59, and CD46 (P < 0.05)." (PMID 22761633, 2012). "An alternative hypothesis that decreased CD55 lymphocyte levels predispose a subset of SLE patients to lymphopenia should not be ignored." (PMID 24592327, 2014). "However, diminished expression of CD55 and/or CD59 leading to enhanced susceptibility to complement-mediated lysis might also have caused lymphopenia." (PMID 25330534, 2014). "Diminished expression of CD55 and/or CD59 was previously reported in SLE patients with lymphopenia and hemolytic anemia." (PMID 25330534, 2014). "Another contributing factor to lymphopenia involves defective CD95/Fas systems and diminished expression of complement regulatory proteins (CD55 and CD59)." (PMID 24860837, 2014). "In a follow-up study an analysis of 40 SLE patients with and without lymphopenia showed that mean fluorescence intensities (MFI) of CD55 and CD59 were diminished on T- and B-cells in lymphopenic patients compared to nonlymphopenic patients." (PMID 24592327, 2014).
multiple myeloma (5 papers, 2013 to 2025). "PIGM expression as validated on protein level using Western blotting, flow cytometry and immunohistochemistry is associated with CD55/CD59 expression on myeloma cell lines and thus impacts on cell surface expressed GPI-anchored receptors." (PMID 24386263, 2013). "The expression of GPI-anchored proteins with known functions in myeloma cells, such as CD55 and CD59 has been demonstrated." (PMID 24386263, 2013). "To further explore the mechanisms that contribute to the refractoriness of myeloma cells toward CD26mAb therapy, we assessed the levels of complement inhibitory proteins (CIP) CD55 and CD59 in myeloma cells incubated with one of five HDACi for 48 hours." (PMID 38284882, 2024). "First, an increase in the expression of CIPs, including CD55 and CD59, protects myeloma cells from complement attack via CDC, leading to refractoriness to mAb." (PMID 38284882, 2024). "Resistance to DARA may result from upregulation of the complement inhibitory proteins CD55 and CD59, downregulation of the DARA target CD38 on myeloma cells or altered expression of the checkpoint inhibitor ligand programmed death ligand-1 (PD-L1) or other mechanisms." (PMID 36359760, 2022).
non-small cell lung carcinoma (5 papers, 2012 to 2025). A group of at least three distinct histological types of lung cancer, including non-small cell squamous cell carcinoma, adenocarcinoma, and large cell carcinoma. "Having shown that CD55 rs2564978 polymorphism effect on the risk of non small-cell lung cancer, we then conduct a dual-luciferase reporter gene assay to assess the effect of CD55 rs2564978 polymorphism on transcriptional activity of the gene." (PMID 28008159, 2017). "This study aims to investigate the role of CD55 variants in the development of non-small cell lung cancer (NSCLC)." (PMID 28008159, 2017). "We determined that CD55 is overexpressed in 76.47% of human non-small cell lung cancer tissue specimens." (PMID 29895866, 2018). "An increased presence of the complement-inhibitory proteins CD55 and CD59 has been observed in non-small cell lung cancer (NSCLC) among various other malignancies, which has been associated with signaling from cytokines." (PMID 40515636, 2025). "Results have shown that in Herceptin treatment for non-small cell lung cancer (NSCLC), neutralization of CD55 and CD59 results in markedly increased Herceptin-mediated complement cytotoxicity." (PMID 31164885, 2019). "In non-small cell lung cancer (NSCLC) cells, CD55 and CD59 were closely correlated with histological types, prognosis and preoperational adjutant chemotherapy of the disease." (PMID 22634835, 2012).